PTTG3P (pituitary tumor-transforming 3, pseudogene)
Synonyms: PTTG3; PTTG1P3; rcPTTG1
Gene: Processed pseudogene on chromosome 8 (66,767,400 to 66,768,005, reverse strand). Ensembl gene ENSG00000213005.
Subcellular location: Cytoplasm; Nucleus
Diseases named in the same sentence as PTTG3P in open-access papers:
PTTG3P is named in the same sentence as 44 diseases in open-access papers, as found by Europe PMC text mining. Sharing a sentence is not in itself a finding about the gene and the disease. The quoted sentences say what the papers report.
hepatocellular carcinoma (12 papers, 2018 to 2025). A malignant tumor that arises from hepatocytes. "For instance, the pituitary tumor-transforming 3 pseudogene (PTTG3P) is upregulated in hepatocellular carcinoma (HCC), functioning as an oncogene." (PMID 40342419, 2025). "It is known that PTTG3P influences tumor growth and metastasis in both cervical cancer and hepatocellular carcinoma." (PMID 32824814, 2020). "Abnormal AKT signalling leads to increased expression of lncRNA PTTG3P and promotes proliferation and migration of hepatoma cells." (PMID 31341758, 2019). "Up-regulation of lncRNA PTTG3P (pituitary tumor-transforming 3, pseudogene) promotes tumor cell growth and metastasis in hepatocellular carcinoma." (PMID 31142627, 2019). "In hepatocellular carcinoma, enforced expression of the lncRNA PTTG3P facilitates cell proliferation, invasion, migration, and metastasis via activation of the PI3K/Akt pathway." (PMID 30619763, 2018). "Recently, the pseudogene-derived lncRNA PTTG3P (pituitary tumor-transforming 3, pseudogene) has been reported to act as an oncogene in gastric cancer 15, hepatocellular carcinoma 16, cervical cancer 17, breast cancer 18, colorectal cancer 19, and pancreatic cancer." (PMID 37705754, 2023). "PTTG3P has a limited protein-coding capacity, and thus is regarded as one long non-coding RNA (lncRNA) implied in tumorigenesis of gastric carcinoma and hepatocellular carcinoma (HCC)." (PMID 30853662, 2019). "We aimed to elucidate the diagnostic efficacy of eight serum lncRNAs HULC, MALAT1, Linc00152, PTENP1, PTTG3P, SPRY4-IT1, UBE2CP3, and UCA1 and their combinations for the diagnosis of hepatocellular carcinoma (HCC)." (PMID 32733618, 2020). "The mechanisms of PTTG3P functions are not yet well understood, but it has been demonstrated that PTTG3P promotes both proliferation and invasion throght upregulation of PTTG1 and is an indicator of bad prognosis in cervical cancer and hepatocellular carcinoma." (PMID 32824814, 2020).
breast carcinoma (11 papers, 2018 to 2024). "We further investigated the associations between pseudogene PTTG3P expression and different clinicopathological characteristics in patients with breast cancer, by using bc-GenExMiner." (PMID 31011629, 2019). "High expression of PTTG3P was also found to be associated with a poor prognosis of breast cancer." (PMID 31011629, 2019). "Previous studies have also reported high expression of PTTG3P in breast cancer and it has been found that PTTG3P expression is inversely correlated with estrogen receptor (ER) and progesterone receptor (PR) status, and high expression of PTTG3P is associated with poor prognosis of breast cancer." (PMID 33845847, 2021). "Previous research has also suggested increased expression of PTTG3P in breast cancer patients, with its elevated levels correlating with unfavorable prognosis." (PMID 39139816, 2024). "In breast cancer, there is a positive relationship between PTTG3P and PTTG1 expression, with high expression indicating a poor prognosis." (PMID 39170694, 2024). "Similar results were also reported in cervical carcinoma and breast cancer cohorts However, role of PTTG3P in PDAC has yet been well understood." (PMID 33298873, 2020). "The analytic result from UALCAN database showed that high expression of pseudogene PTTG3P suggested unfavorable prognosis of patients with breast cancer (P = 0.048)." (PMID 31011629, 2019). "Next, the prognostic value of pseudogene PTTG3P mRNA in human breast cancer was further evaluated, using three online databases, including the Kaplan-Meier Plotter, UALCAN, and OncoLnc." (PMID 31011629, 2019). "Oncomine analysis revealed that expression of PTTG3P in breast cancer tissues was significantly higher than that in normal tissues." (PMID 31011629, 2019). "Next, Oncomine analysis of cancer versus normal samples was used to analyze the expression profile of pseudogene PTTG3P in human breast cancer." (PMID 31011629, 2019). "In this study, we first determined the expression level of PTTG3P in breast cancer, based on bioinformatics analyses and experimental validation." (PMID 31011629, 2019). "Pseudogene PTTG3P expression in breast cancer tissues was markedly higher than that in normal tissues." (PMID 31011629, 2019). "Subsequently, the Kaplan-Meier Plotter, UALCAN, and OncoLnc databases were used to study the prognostic role of PTTG3P in breast cancer, and the analytic results displayed that high expression of PTTG3P indicated poor RFS, OS, and DMFS." (PMID 31011629, 2019). "For further validation, we also detected the expression of pseudogene PTTG3P in clinical breast cancer samples." (PMID 31011629, 2019). "In this study, high expression of pseudogene PTTG3P in breast cancer was confirmed, and increased expression of PTTG3P indicated a poor prognosis of breast cancer." (PMID 31011629, 2019). "Based on the ceRNA mechanism, expression of downstream miRNAs of PTTG3P in breast cancer samples should be decreased when compared with normal controls." (PMID 31011629, 2019). "All evidence taken together, by combining bioinformatics analysis and experimental validation, we demonstrated that PTTG3P was significantly overexpressed in human breast cancer." (PMID 31011629, 2019). "The expression profile of pseudogene PTTG3P in human breast cancer was first determined by using the SAGE (Serial Analysis of Gene Expression) Digital Gene Expression Display." (PMID 31011629, 2019). "Altogether, based on bioinformatics analysis and experimental validation, we provided a reliable integrated analysis of the pseudogene PTTG3P expression pattern, prognostic value, and potential regulatory mechanisms in breast cancer." (PMID 31011629, 2019). "Identifying the co-expressed genes would facilitate a better understanding of potential functions of PTTG3P in breast cancer." (PMID 31011629, 2019). "Herein, we first assessed the expression pattern of PTTG3P in human breast cancer by data mining and experimental validation." (PMID 31011629, 2019).
breast carcinoma (continued). "qRT-PCR for clinical samples also demonstrated a high expression level of PTTG3P in breast cancer tissues when compared with their matched normal tissues." (PMID 31011629, 2019). "Recently, PTTG3P expression has a relationship with breast cancer and pancreatic cancer." (PMID 34132347, 2021). "PTTG1 has been demonstrated to be a key target of PTTG3P in both breast cancer and HCC8,11." (PMID 33298873, 2020). "Taken together, our findings suggest that increased expression of pseudogene PTTG3P may be used as a promising prognostic biomarker and novel therapeutic target for breast cancer." (PMID 31011629, 2019). "All these findings indicate that PTTG3P may serve as a poor predictor of prognosis of patients with breast cancer." (PMID 31011629, 2019). "Then, the prognostic significance of PTTG3P expression in breast cancer was also analyzed." (PMID 31011629, 2019). "Finally, we explored several potential mechanisms of PTTG3P in breast cancer, including construction of the pseudogene PTTG3P-miRNA-mRNA network, analysis of co-expressed genes, and assessment of its correlation with parental genes PTTG1 and -2." (PMID 31011629, 2019). "To summarize, these results demonstrate that pseudogene PTTG3P expression may play an unfavorable role in patients with breast cancer." (PMID 31011629, 2019). "In summary, pseudogene PTTG3P may serve as a novel prognostic biomarker and a therapeutic target for patients with breast cancer." (PMID 31011629, 2019). "In addition, PTTG3P plays an important role in breast cancer and pancreatic cancer." (PMID 34660259, 2021). "Notably, the expression, function, and corresponding regulatory mechanisms of PTTG3P in breast cancer remain unclear and need to be further elucidated." (PMID 31011629, 2019). "Pseudogene PTTG3P expression was not significantly dysregulated in all cancer tissues when compared with corresponding normal tissues, including breast cancer." (PMID 31011629, 2019). "Our findings also supported that PTTG3P may upregulate PTTG1 expression, thus functioning as an oncogene in breast cancer." (PMID 31011629, 2019).
gastric cancer (11 papers, 2017 to 2025). A primary or metastatic malignant neoplasm involving the stomach. "Another study demonstrated that PTTG3P can augment the in vitro proliferation and invasion of gastric cancer (GC), serving as an indicator of an unfavorable prognosis." (PMID 40877987, 2025). "Positive correlation between PTTG3P and FoxM1 were also observed in liver cancer (R = 0.593, P = 0.000), colorectal cancer (R = 0.341, P = 0.000) and gastric cancer (R = 0.900, P = 0.000) tissues by analyzing TCGA and GEO databases." (PMID 33298873, 2020). "In line with some data obtained in our study, previous research shows that PTTG3P is highly expressed in gastric cancer tissues, and promotes cell proliferation, migration and invasion in vitro and in vivo, functioning as an independent negative prognostic biomarker." (PMID 31340767, 2019). "Moreover, higher level of PTTG3P has been reported to be correlated with shorter disease-free survival and overall survival in patients with gastric cancer." (PMID 29803224, 2018). "The pseudogene-derived lncRNA PTTG3P has been reported to act as an oncogene in gastric cancer and HCC, but the molecular mechanism how PTTG3P interacts with miRNAs in HCC remains poor." (PMID 31340767, 2019). "However, the role of pituitary tumour‐transforming 3, pseudogene (PTTG3P) in gastric cancer (GC) remains unknown." (PMID 28631396, 2017).
cervical carcinoma (5 papers, 2019 to 2023). A carcinoma arising from either the exocervical squamous epithelium or the endocervical glandular epithelium. "Moreover, PTTG3P was correlated with a higher stage of uterine cervix carcinoma." (PMID 32824814, 2020).
colorectal cancer (5 papers, 2020 to 2024). A primary or metastatic malignant neoplasm that affects the colon or rectum. "PTTG3P promoted cell proliferation and glycolysis in colorectal cancer and also promoted metastasis by sponge-absorbing microRNA-155-5P." (PMID 39170694, 2024). "Until now, lncRNA pituitary tumor-transforming 3, pseudogene (PTTG3P) biological function in colorectal cancer (CRC) further needs to be clarified." (PMID 34132347, 2021).
esophageal squamous cell carcinoma (5 papers, 2020 to 2023). Esophageal squamous cell carcinoma (ESCC) is a type of esophageal carcinoma (EC) that can affect any part of the esophagus, but is usually located in the upper or middle third. "PTTG3P expression was found to increase in esophageal squamous cell carcinoma tissues and cell lines." (PMID 32185172, 2020). "Enhanced expression of PTTG3P greatly stimulated migration and invasion of esophageal squamous cell carcinoma through upregulating expression levels of PTTG1 and PTTG2." (PMID 32185172, 2020). "In vitro studies have confirmed that exogenously the overexpression of PTTG3P promotes the transcription of its parental genes PTTG1 and PTTG2 in esophageal squamous cell carcinoma cells." (PMID 32824814, 2020). "Furthermore, our specimens confirmed that PTTG3P was overexpressed in stomach adenocarcinoma (STAD) and esophageal squamous cell carcinoma (ESCA)." (PMID 34660259, 2021). "Also, our specimens confirmed PTTG3P overexpression in stomach adenocarcinoma (STAD) and esophageal squamous cell carcinoma (ESCA)." (PMID 34132347, 2021). "High expression levels of PTTG3P, PTTG1, and PTTG2 have been observed in esophageal squamous cell carcinoma (ESCC) patients and cell lines." (PMID 36770654, 2023).
liver cancer (4 papers, 2019 to 2022). An epithelial or non-epithelial malignant neoplasm that arises from the liver. "The upregulation of PTTG3P is positively correlated with a poor prognosis of liver cancer patients." (PMID 31341758, 2019). "It has been shown that the expression of PTTG3P in liver cancer is significantly increased." (PMID 31341758, 2019). "Huang, found that long chain noncoding RNA PTTG3P by raising PTTG1 and activating PI3K/AKT signaling pathway to promote cell growth and metastasis of liver cancer." (PMID 35033076, 2022). "Therefore, PTTG3P may be a potential target for the prevention and treatment of liver cancer." (PMID 31341758, 2019). "Expression and localization of PTTG3P were analyzed using quantitative real-time polymerase chain reaction (qRTPCR) and in situ hybridization (ISH) in two patients with liver cancer." (PMID 31341758, 2019).
pancreatic cancer (4 papers, 2020 to 2023). "Recently, a study demonstrated that FoxM1-mediated transcription of lncRNA PTTG3P promotes tumorigenesis and metastasis of pancreatic cancer." (PMID 37705754, 2023).
gastric tumor (3 papers, 2017 to 2024). "Consistently, PTTG3P has been demonstrated to promote gastric tumor cell proliferation and invasion." (PMID 29803224, 2018).
glioma (3 papers, 2015 to 2022). A benign or malignant brain and spinal cord tumor that arises from glial cells (astrocytes, oligodendrocytes, ependymal cells). "Six pseudogenes (SP3P, ANXA2P3, PTTG3P, LPAL2, CLCA3P, and TDH) were reported to be associated with overall survival in glioma." (PMID 36333286, 2022). "As the pseudogene of PTTG, PTTG3P may play as an oncogene in glioma, which played as a risky gene." (PMID 25880120, 2015). "A prior report that constructed another signature with six pseudogenes (SP3P, ANXA2P3, PTTG3P, LPAL2, CLCA3P, and TDH) for prediction of glioma patient survival." (PMID 31681595, 2019).
triple-negative breast carcinoma (3 papers, 2019 to 2021). An invasive breast carcinoma which is negative for expression of estrogen receptor (ER), progesterone receptor (PR), and human epidermal growth factor receptor 2 (HER2). "Pseudogene PTTG3P was significantly upregulated in basal-like or triple-negative breast cancer when compared with their counterparts (basal-like status: p < 0.0001; triple-negative status: p < 0.0001)." (PMID 31011629, 2019).
Sepsis (2 papers, 2022). Sepsis is defined as life-threatening organ dysfunction caused by a dysregulated host response to infection. "In summary, the present study identified SIGLEC9, TSPO, CKS1B, and PTTG3P as the genetic biomarkers and established a four-gene-based model for the effective diagnosis and risk prediction of sepsis/se-ARDS based on gene co-expression network." (PMID 35844622, 2022). "Further correlation analysis based on SIGLEC9, TSPO, CKS1B, and PTTG3P was carried out to identify the potential interactions and effects of these diagnostic biomarkers during sepsis/se-ARDS development." (PMID 35844622, 2022). "The expressions of four genes were remarkably related to each other, and it is apparent that the highly positive correlations between SIGLEC9 and TSPO and between CKS1B and PTTG3P were spectacularly remarkable at all the stages of sepsis/se-ARDS progression." (PMID 35844622, 2022). "Both SIGLEC9 and TSPO were significantly upregulated on sepsis day 0 and then descended a bit more on sepsis day 7 (***P<0.001) during sepsis development, while both CKS1B and PTTG3P appeared to be steadily upregulated on sepsis day 0 and day 7 (*P<0.05)." (PMID 35844622, 2022). "Afterwards, a sepsis/se-ARDS risk nomogram model that involves SIGLEC9, TSPO, CKS1B, and PTTG3P as the independent predictors was constructed." (PMID 35844622, 2022). "SIGLEC9, TSPO, CKS1B, and PTTG3P all exhibited remarkable changes of upregulations in the sepsis group compared with control group in both datasets with P<0.05 (except for CKS1B in GSE28750), which proved the great diagnostic and predictive performance of these four biomarkers." (PMID 35844622, 2022). "Besides, SIGLEC9, TSPO, CKS1B and PTTG3P were considerably correlated with the infiltration of various immune cells including neutrophils and monocytes during sepsis/se-ARDS." (PMID 35844622, 2022). "Moreover, the levels of immune cell infiltration in the progress of sepsis/se-ARDS promoted their further correlation analysis based on SIGLEC9, TSPO, CKS1B, and PTTG3P, the diagnostic biomarkers identified in the study." (PMID 35844622, 2022). "During the development of sepsis/se-ARDS, the expressions of the identified biomarkers including SIGLEC9, TSPO, CKS1B and PTTG3P were all regulated remarkably and generally exhibited notable correlations with the stages of sepsis/se-ARDS." (PMID 35844622, 2022).
childhood asthma (1 paper, 2025). "The diagnostic and prognostic value of lncRNAs is gaining traction, with the PTTG3P/miR-192-3p/CCNB1 axis emerging as a potential biomarker for childhood asthma, underscoring their promise in non-invasive disease monitoring." (PMID 40806181, 2025).
colon cancer (1 paper, 2022). "In addition, METTL3 increases the expression of PTTG3P through an m6A/IGF2BP2-dependent mechanism and regulates the PTTG3P/YAP1 axis to induce colon cancer cell proliferation and promote colon cancer progression." (PMID 35614935, 2022).
IgA nephropathy (1 paper, 2022). "Expression of PTTG3P has been shown to be up-regulated in samples obtained from patients with IgA nephropathy compared with normal samples." (PMID 35193592, 2022). "Notably, expression of PTTG3P in urine samples has been correlated with expression of PTTG3P in intra-renal samples of IgA nephropathy cases." (PMID 35193592, 2022).
lentivirus infection (1 paper, 2018). Virus diseases caused by the Lentivirus genus. "To further confirm the effect of PTTG3P on cell proliferation and viability in HCC, we constructed HepG2 and Hep3B cells stably over-expressing PTTG3P by lentivirus infection." (PMID 29803224, 2018).
liver diseases (1 paper, 2020). "The levels of serum HULC, MALAT1, Linc00152, PTTG3P, SPRY4-IT1, UBE2CP3, and UCA1 were significantly higher in HCC patients than in patients with benign liver diseases and healthy controls, whereas serum PTENP1 was significantly decreased in HCC patients compared with healthy participants." (PMID 32733618, 2020).
lung adenocarcinoma (1 paper, 2025). A carcinoma that arises from the lung and is characterized by the presence of malignant glandular epithelial cells. "In this comprehensive study, we explored the roles of the pituitary tumor-transforming gene (PTTG) family, including PTTG1, PTTG2, and the pseudogene PTTG3P in lung adenocarcinoma (LUAD)." (PMID 40877987, 2025).
lung squamous cell carcinoma (1 paper, 2020). "Based on TCGA data, we found that in HNSCC PTTG3P alteration is mild and is estimated to be around 1.39, compared to the highest fold change of PTTG3P observed in lung squamous cell carcinoma (LUSC), 7.26-fold change." (PMID 32824814, 2020).
pancreatic ductal adenocarcinoma (1 paper, 2020). An infiltrating adenocarcinoma that arises from the epithelial cells of the pancreas. "However, the biological role and clinical significance of PTTG3P in pancreatic ductal adenocarcinoma (PDAC) remain unclear." (PMID 33298873, 2020).
pharynx tumors (1 paper, 2020). "As was the case with PTTG3P, the highest upregulation was observed in pharynx tumors compared to oral and larynx locations." (PMID 32824814, 2020). "Moreover, the highest upregulation of PTTG3P expression was observed in pharynx tumors compared to oral and larynx locations, and instances of PTTG1 and PTTG2 were significantly upregulated in HNSCC tumor tissues compared with normal samples." (PMID 32824814, 2020). "A higher expression of PTTG3P was observed in pharyngeal tumors with HPV status." (PMID 32824814, 2020).